PDGFRA (platelet derived growth factor receptor alpha)
Diseases named in the same sentence as PDGFRA in open-access papers (continued):
Sharing a sentence is not in itself a finding about the gene and the disease.
rhabdomyosarcoma (9 papers, 2012 to 2025). A rare aggressive malignant mesenchymal neoplasm arising from skeletal muscle. "PDGFRα is selectively upregulated in rhabdomyosarcoma, and PDGFRα expression is associated with poor prognosis." (PMID 24359404, 2013). "PDGFR gene expression analysis in pediatric rhabdomyosarcoma demonstrated decreased failure‐free survival for patients with tumors that overexpressed either PDGFRα or PDGFRβ mRNA." (PMID 33474828, 2021). "In another study, the rhabdomyosarcoma‐derived cell line A204 was associated with PDGFRα signaling, and INKA scoring of the underlying data accordingly ranks PDGFRα in second place." (PMID 30979792, 2019). "In a subsequent study, a BMS-754807-resistant rhabdomyosarcoma cell line model was developed, which revealed that the platelet-derived growth factor receptor alpha (PDGFRα) plays a role in acquired resistance to BMS-754807." (PMID 23525758, 2013). "Treatment with imatinib or a neutralizing PDGFRα antibody inhibited growth of alveolar rhabdomyosarcoma in a mouse model." (PMID 24359404, 2013). "Furthermore, platelet-derived growth factor receptor alpha (PDGFRA), a receptor tyrosine kinase amplified in IMGs and linked with poor prognosis, has been effectively targeted by CAR T cells in other cancers like rhabdomyosarcoma." (PMID 40647477, 2025). "In contrast, EGFR (epidermal growth factor receptor), VEGFR2 (VEGF receptor 2 = KDR), and PDGFRA (platelet-derived growth factor receptor α) were overexpressed in embryonal, and ERBB3 (ErbB3) in alveolar and unclassified rhabdomyosarcomas." (PMID 23227212, 2012).
synovial sarcoma (9 papers, 2017 to 2025). "PDGF-driven activation of PDGFRA in synovial sarcomas and activating mutations of PDGFRA in GIST parallel the activation of PDGFRA in KSHV-positive and KSHV-negative mouse-KS, respectively." (PMID 29985958, 2018). "Findings in human synovial sarcoma models has shown that despite strong inhibition of its main PDGFRα/β target, the over activation of compensatory pathways suggests the need for combinatorial partner to restore effective inhibition." (PMID 40121334, 2025). "For instance, synovial sarcoma and undifferentiated sarcoma showed high expression for one or more of the markers with predominant high expression of PDGFRα in 58.4% and 56.2% of cases respectively." (PMID 39534097, 2024). "Most cases of synovial sarcoma (45.8%) and 43.7% of patients with undifferentiated sarcoma exhibited high expression of PDGFRα while 41.6% of MPNST showed high expression to PDGFRβ." (PMID 39534097, 2024). "Specifically, 45.8% (n=11) of synovial sarcoma cases and 43.7% (n=7) of patients with undifferentiated sarcoma showed high expression of PDGFRα." (PMID 39534097, 2024). "In addition, we have previously demonstrated the sensitivity of a subset of synovial sarcoma (SS) to inhibition of PDGFRA, a kinase often upregulated in this disease." (PMID 34841430, 2022). "Focusing on the synovial sarcoma subtype, they found several new RTK dependencies including ALK, PDGFRα and MET which were functionally tested in preclinical in vivo experiments and whose expression was shown to be elevated in a subset of synovial sarcoma patient specimens." (PMID 35171456, 2022).
chordoma (8 papers, 2010 to 2022). Chordomas are rare malignant tumors arising from embryonic remnants of the notochord in axial skeleton. "Dasatinib, a small molecule inhibitor of the Src family of kinases, PDGFRα/β, and c-KIT, is currently the only TKI that has demonstrated activity against both chondrosarcoma (CS) and chordoma in a phase II clinical trial." (PMID 36430263, 2022). "Successively, in a molecular/biochemical analyses of the three receptors targeted by IM (PDGFRB, PDGFRA, and KIT) in a series of 31 chordoma patients, it was proven that PDGFRB was highly expressed and phosphorilated whereas PDGFRA and KIT were less expressed but equally activated." (PMID 20109225, 2010).
lung adenocarcinoma (8 papers, 2013 to 2024). A carcinoma that arises from the lung and is characterized by the presence of malignant glandular epithelial cells. "Our investigation revealed that COL1A1, COL1A2, FAP, and PDGFRA are effective markers for characterizing CAF subgroups in most lung adenocarcinoma datasets." (PMID 39034310, 2024). "The driver genes involved in lung adenocarcinoma include KRAS, EGFR, ALK, and BRAF, and those implicated in lung squamous cell carcinoma (LSCC) include PIK3CA, FGFR1, EGFR, PDGFRA, and DDR2." (PMID 26373952, 2015). "Five genes were flagged as mutant in all 8 lung adenocarcinoma samples namely RET, APC, FGFR3, NPM1 and PDGFRA when the least stringent QBVD threshold was applied (QBVDi = 71)." (PMID 23922754, 2013).
lymph node metastasis (8 papers, 2012 to 2025). "Through immunohistochemical analysis of invasive ductal breast carcinoma tissues, PDGFRA was associated with lymph node metastasis and HER2 expression." (PMID 36979654, 2023). "Future studies should validate these findings in larger cohorts and explore the predictive value of THBS4 and PDGFRA as biomarkers of PTMC lymph node metastasis." (PMID 40303998, 2025). "Our study demonstrates the potential clinical utility of using THBS4 and PDGFRA as biomarkers to predict PTMC lymph node metastasis." (PMID 40303998, 2025). "High expression of PDGF, PDGFRA, and PDGFRB were remarkably associated with lymph node metastasis and poor OS, as determined by immunohistochemistry." (PMID 32235327, 2020). "Subsequently, through immunohistochemical analysis with tissue staining and comparison with clinicopathological parameters, we found that high expression of PDGF and PDGFRA correlated significantly with lymph node metastasis." (PMID 32235327, 2020). "Only a marginally significant correlation was found between PDGFRA mRNA and lymph node metastasis (p = 0.064)." (PMID 32235327, 2020). "The high expression of PDGF and PDGFRA correlated significantly with lymph node metastasis (p = 0.010 and p = 0.005, respectively)." (PMID 32235327, 2020). "Overexpression of PDGFRA and PDGFRB is associated with lymph node metastasis and poor prognosis." (PMID 32235327, 2020). "Among these genes, PDGFRA and CAV1 expression were significantly more frequent in the NST components of the MpBC cases with lymph node metastasis than in the NST components of those without metastasis, thereby supporting the GSEA results." (PMID 36707876, 2023). "PDGFRA and CAV1 expression were both significantly more frequent in the NST components of MpBC cases with lymph node metastasis than in the NST components of those without metastasis, supporting the GSEA results." (PMID 36707876, 2023).
mastocytosis (8 papers, 2009 to 2022). A clonal myeloproliferative neoplasm characterized by the proliferation and accumulation of neoplastic mast cells in one or multiple organs or organ systems. "FDA-approved avapritinib (approval: Jan 9, 2020, brand name Ayvakit) is used in adults with unresectable or metastatic GIST who harbor a platelet-derived growth factor receptor alpha (PDGFRA) exon 18 mutation and for advanced and indolent systemic mastocytosis (in phase 2 development)." (PMID 35216365, 2022). "Besides inhibition of BCR-ABL, nilotinib has also shown in vitro activity against other kinases, particularly PDGFRα and KIT, which has led to the investigation of its potential clinical utility in diseases driven by these kinases such as gastrointestinal stromal tumors (GISTs) and mastocytosis." (PMID 32346366, 2020).
cutaneous melanoma (7 papers, 2016 to 2023). A primary melanoma arising from atypical melanocytes in the skin. "Gene mutations affecting the MAPK pathway, including those in C-KIT and platelet-derived growth factor receptor alpha (PDGFRA), are more common in acral melanoma than in cutaneous melanoma." (PMID 34149718, 2021).
leiomyosarcoma (7 papers, 2016 to 2024). An uncommon, aggressive malignant smooth muscle neoplasm, usually occurring in post-menopausal women. "The tumors are definitively diagnosed with histopathology and immunohistochemistry, with leiomyosarcoma showing actin and desmin positive reactivity consistent with smooth muscle cell origin and CD117, CD34, PDGFRA, and DOG1 negativity." (PMID 38915340, 2024). "We present a case of a 43-year-old patient operated on for a primary mesenteric leiomyosarcoma with a positive immunostain for DOG1, despite having no KIT or PDGFRa mutations on molecular analysis." (PMID 35755504, 2022). "Accordingly, we observed PDGFRA amplifications also in 5/12 leiomyosarcomas (data not shown)." (PMID 34312479, 2021).
urothelial bladder cancer (7 papers, 2020 to 2025). "Subcluster F0 was the primary fibroblast type in PT and M and strongly expressed PDGFRA and CXCL12, similar to that in the iCAFs described in bladder urothelial carcinoma." (PMID 35184420, 2022). "Until now, the roles of PDGFRA, OLR1, RAC3, PDF, OAS1, and SH3BP2 in bladder urothelial carcinoma remain largely unexplored." (PMID 32733809, 2020). "On the contrary, CAFs promote tumorigenesis in urothelial bladder carcinoma via multiple markers, including alpha smooth muscle actin, CD90/Thy-1, platelet-derived growth factor receptor-alpha and -beta (PDGFR-α/-β) and especially in advanced stages significantly increased FAP-expression." (PMID 37763225, 2023).
anaplastic astrocytoma (6 papers, 2013 to 2024). "This PDGFRα staining, most likely associated with the Golgi apparatus, was focal in ependymomas and was also present in the NHERF1-negative anaplastic ependymoma and anaplastic astrocytoma cases screened." (PMID 25775275, 2015).
Astigmatism (6 papers, 2011 to 2025). A type of refraction error associated with abnormal curvatures on the anterior and/or posterior surface of the cornea. "The role of PDGFRA extends beyond astigmatism, with variants previously associated with a decreased risk of high myopia, as well as variations in lens thickness and anterior chamber depth, highlighting its potential pleiotropic influence on ocular development." (PMID 41320768, 2025). "Corneal astigmatism is reportedly associated with polymorphisms of the platelet-derived growth factor receptor alpha (PDGFRA) gene region in Asian populations of Chinese, Malay, and Indian ancestry and populations of European ancestry." (PMID 37752244, 2023). "Corneal astigmatism is reportedly associated with single-nucleotide polymorphisms (SNPs) of the platelet-derived growth factor receptor alpha (PDGFRA) gene region on chromosome 4q12." (PMID 37752244, 2023). "To date, the known genes and candidate genes associated with astigmatism are PDGFRA, CLDN7, ACP2, and TNFAIP8L, of which PDGFRA has been shown to increase the risk of astigmatism 1.12 times." (PMID 35885949, 2022). "At the lead SNP rs7677751 in PDGFRA, the frequency of the risk T-allele ranged from 0.19 to 0.26 in the five cohorts and conferred a 26% higher risk of corneal astigmatism than the C allele (OR = 1.26, 95% CI = 1.16–1.36) in the meta-analysis across all five studies." (PMID 22144915, 2011). "Our discovery at PDGFRA thus suggests that part of the underlying biological pathway responsible for astigmatism development is common to multiple populations, although there may be population-specific genetic variants that our current study is not sufficiently powered to identify." (PMID 22144915, 2011). "Given that most children in the cohort had WTR CA and ATR IA, the absence of any associations with RA may reflect the potential role of the PDGFRA gene in coordinating the scaling of J0(IA) and CR to maintain a state of no astigmatism in children." (PMID 41320768, 2025).
Cirrhosis (6 papers, 2012 to 2025). A chronic disorder of the liver in which liver tissue becomes scarred and is partially replaced by regenerative nodules and fibrotic tissue resulting in loss of liver function. "Additionally, the scar-associated macrophages (SAMs) differentiated by markers such as TREM2, CD9, SPP1, TNFSF12, and LGALS3 and PDGFRA+ myofibroblasts had an increased proportion in patients with cirrhosis." (PMID 39889710, 2025). "Indeed, scRNA-seq analysis from patients with cirrhosis of different etiologies identified a population of PDGFRA+ ECM-expressing mesenchymal cells populating the fibrotic niche and predicted to derive from HSCs based on RNA velocity analysis." (PMID 40955668, 2025). "80–90% of human HCC arise in the setting of a cirrhotic liver, in which HSCs have been activated, so we first performed IHC analysis to determine whether PDGFRα and PDGFRβ levels are elevated in human cirrhosis and HCC." (PMID 24667490, 2014). "We found increased PDGFRα in human liver specimens with fibrosis and cirrhosis." (PMID 24667490, 2014). "In addition, PDGF-CC a selective ligand of PDGFRα, whose overexpression in liver-specific transgenic mice has been shown to induce cirrhosis and HCC, was also increased in KO." (PMID 22761897, 2012). "Pseudotime analysis also suggested that PDGFRα+ CAFs and RGS5+ CAFs from cirrhosis and HCC patients also diverged from HPCs, as we found in the rat HCC model." (PMID 39827226, 2025).
colitis (6 papers, 2022 to 2024). Inflammation of the colon. "The findings indicated that colonic transit disorder in DSS-induced colitis mice is caused by the down-regulation of PDGFRα+ cells / SK3 channel expression." (PMID 39689119, 2024). "Our data combined with the results of the transgenic Adamdec1 knockout phenotype indicate that induction of Adamdec1 may be a secondary defensive response to inflammation and that increased ADAMDEC1 contributes to loss of PDGFRα+ cells in DSS-induced colitis." (PMID 35563399, 2022). "Up to now, although considerable progress has been made in studying the mechanism of colonic motility disorder, little is known about the effect of PDGFRα+, another interstitial cell, on colonic motility disorder in patients with colitis." (PMID 39689119, 2024). "The functional down-regulation of SK3 signaling pathway in PDGFRα+ cells in colitis group destroyed the coordination between ICC and PDGFRα+ cell in SIP syncytium, disrupted the regular colon transit, and finally led to colon transit disorder in colitis mice." (PMID 39689119, 2024). "The results showed that SK3 channels localized to stellate-shaped or spindle-shaped cells in the smooth muscle tissue, and the number of SK3 channels colocalized PDGFRα+ cells in the DSS-colitis mouse group was much lower than that in the control group." (PMID 39689119, 2024). "Less SK3 channel colocalization with PDGFRα+ cells was observed in the colitis mouse group than in the control group." (PMID 39689119, 2024). "Based on the assumption that PDGFRα expression reflects the identification of PDGFRα+ cells, we examined the expression of PDGFRα in the colonic smooth muscle tissue from the colitis experimental group and control group." (PMID 39689119, 2024). "In this study, the contributions of the SK3 signalling pathway in PDGFRα+ cells to colitis-induced colonic transit dysmotility were investigated in DSS-induced colitis mice." (PMID 39689119, 2024). "PDGFRα protein expression was significantly lower in the colonic smooth muscle tissue of colitis mice (46.6 ± 3.7%; P < 0.05; n = 7) than in that of control mice." (PMID 39689119, 2024). "In our DSS-induced colitis model, the fibroblast marker PDGFRα displayed a distinct expression pattern, being undetectable at baseline (D0), peaking during early repair (D6), and decreasing by D12 and D18." (PMID 38674054, 2024). "Next, we wanted to know if there would be a change in the quantity of enhanced green fluorescent protein (eGFP+) PDGFRα+ cells or other physiological changes in DSS-induced colitis tissue from PdgfrαeGFP/+ mice." (PMID 35563399, 2022). "Adamdec1 was predominantly expressed in CD45− PDGFRα+ cells in DSS-induced colitis mice, with only minimal expression in CD45+ CD64+ macrophages." (PMID 35563399, 2022). "We believe that this result may be caused by the transmission disorder of the proximal colon in the colitis group; this result may be due to the fact that more PDGFRα+ cells are distributed in the distal colon than in the proximal colon." (PMID 39689119, 2024). "Therefore, this study revealed the regulation of the SK3 signalling pathway in PDGFRα+ cells in mice with colitis." (PMID 39689119, 2024). "Therefore, how the P2Y1 receptor on PDGFRα+ cells in individuals with colitis regulates the SK3 signalling pathway through purinergic neurotransmitters will be further explored." (PMID 39689119, 2024). "Additionally, according to the transcript level detected using RT‒PCR, the expression of the PDGFRα gene was also 45.7 ± 3.3% lower (P < 0.05; n = 7) in the colitis mice than in the control mice." (PMID 39689119, 2024). "Therefore, this study focused on the role of the SK3 signalling pathway in PDGFRα+ cells in colitis-induced colon transit dysmotility." (PMID 39689119, 2024). "Additionally, PDGFRA protein expression was decreased in all DSS-induced colitis mice, and increased in Rec 7D." (PMID 35563399, 2022).
colitis (continued). "The expression levels of mRNA and protein of PDGFRα and SK3 channels in colon of mice with colitis were decreased." (PMID 39689119, 2024). "The colitis group exhibited reduced protein and gene expression levels of SK3 and PDGFRα compared to the control group." (PMID 39689119, 2024). "Thus, we further confirmed that the effect of the SK3 signalling pathway on PDGFRα+ cells in colitis mice was decreased; namely, the relaxation effect on smooth muscle was weakened, which may be the main cause of colonic transmission disorders and even diarrhoea in colitis mice." (PMID 39689119, 2024). "As in our model, KO mice of RSPO3 in PdgfRα+ stromal cells showed a decreased number of PCs during homeostasis, while being hypersensitive to DSS-induced colitis." (PMID 35190527, 2022). "As a method to further confirm the low expression of PDGFRα and SK3 channels in colitis mice, we used CMMC as the main form of dynamic colonic transmission to observe the difference between the control group and colitis group." (PMID 39689119, 2024). "Furthermore, this research broadens the existing knowledge on the function of PDGFRα+ cells and their specific SK3 channels, offering a potential novel approach for investigating more efficient therapies for colitis." (PMID 39689119, 2024). "PDGFRα+ cells significantly overexpressed Adamdec1 mRNAs and protein in DSS-induced colitis mice." (PMID 35563399, 2022). "However, the role of PDGFRα+ cells in colonic dysmotility in colitis disease has not been previously studied." (PMID 39689119, 2024). "If the balance between depolarizing (activation of ANO1 channels in ICC) and hyperpolarizing (activation of SK3 channels in PDGFRα+ cells) is disrupted, as occurs in DSS colitis, one might expect greater depolarization and greater contractile responses to PAR1 activation." (PMID 36202914, 2022).